OGN (osteoglycin)
Diseases named in the same sentence as OGN in open-access papers (continued):
Sharing a sentence is not in itself a finding about the gene and the disease.
OGN also shares sentences with these, for which no sentence is quoted: invasive ductal breast carcinoma (4 papers); colorectal adenoma (3); infection (3); Arthritis (2); hepatocellular carcinoma (2); vaginal cancer (2); adenoma (1); biliary atresia (1); brain tumors (1); calcification (1); cardiac hypertrophy (1); cardiac interstitial fibrosis (1); cardiac ischemia (1); CNS tumors (1); connective tissue diseases (1); coronary atherosclerosis (1); COVID-19 (1); endocrine system disorder (1); glaucoma (1); Glucose intolerance (1); Hypertension (1); leiomyoma (1); myelofibrosis (1); non-small cell lung carcinoma (1); pancreatic cancer (1); papillary renal cell carcinoma (1); peripheral artery disease (1); prostate carcinoma (1); psoriasis (1); renal fibrosis (1).
A further 5 diseases each share a sentence with OGN in 1 paper.